LAMA4 (laminin subunit alpha 4)
Diseases named in the same sentence as LAMA4 in open-access papers (continued):
Sharing a sentence is not in itself a finding about the gene and the disease.
breast carcinoma (9 papers, 2013 to 2024). "In breast carcinomas, an increase in LAMA4 expression marks the transition from pre-malignant lesions to malignant carcinomas, while in well-developed tumors an overexpression of LAMA4 mRNA is associated with shorter relapse-free survival." (PMID 31781574, 2019). "Furthermore, high expression of LAMA4 has been associated with invasiveness in breast cancer." (PMID 32929348, 2020). "A previous study showed that LAMA4 promotes tumor re-initiation and metastatic cell proliferation and colonization in breast cancer." (PMID 32929348, 2020). "In certain breast cancer subtypes, increased LAMA4 expression was noted to contribute to the chromatin remodeling mechanisms that are a part of cancer progression." (PMID 32038103, 2020). "Expression levels of the strongest co-regulated gene pair, SORCS2 as a host and LAMA4 as a target, correlated negatively (R = −0.57, p < 2.2 × 10−16), when analyzed in a basal-like breast carcinoma sample subset of TCGA (N = 190)." (PMID 31781574, 2019). "Our study showed LAMA4 mRNA (p = 0.001) and protein (p = 0.005) expression in TNBC tissue samples were elevated compared with adjacent normal tissue samples, and LAMA4 was mainly expressed in the cytoplasm of breast carcinoma cells." (PMID 29434522, 2018). "For example, LAMA4 was highly expressed in breast cancer and promoted cell invasion." (PMID 36539799, 2022). "We inhibited expression of IGFBP6 gene in a model cell line for basal-like breast carcinoma MDA-MB-231, then traced secondary and tertiary effects of this knockdown to LAMA4, a laminin encoding gene that contributes to the phenotype of triple-negative breast cancer." (PMID 31781574, 2019). "Immunohistochemical analysis was performed to study its expression and location, the result showed LAMA4 was mainly expressed in the cytoplasm of breast carcinoma cells, 32 patients of the samples had a high expression of the LAMA4 while the other 8 patients have a low expression." (PMID 29434522, 2018). "Previous reports indicate that MIR539 expression is downregulated in breast cancer tissues and cell lines, and MIR539 acts as a tumor suppressor by targeting epidermal growth factor receptor, specificity protein 1, or laminin subunit alpha 4 expression." (PMID 39145770, 2024). "LAMA4-regulating miRNA miR-4274 and its host gene SORCS2 were highlighted as intermediate regulators of the expression levels of LAMA4, which correlated in a basal-like breast carcinoma sample subset of TCGA to the levels of SORCS2 negatively." (PMID 31781574, 2019). "Taken together, observations concerning LAMA4, its regulating miRNA miR-4274 and its host gene SORCS2, point at a substantial role played by secondary and tertiary effects produced by a transcriptional knockdown of IGFBP6 in basal-like breast carcinoma cells." (PMID 31781574, 2019). "While no increase was found in COL5A2 expression after treatment with β-estradiol or in COL5A2 and LAMA4 after treatment with TGFβ in ER-positive and -negative breast carcinoma cells, respectively, all other gene expression levels increased significantly after treatments." (PMID 23441215, 2013).
gastric cancer (9 papers, 2021 to 2024). A primary or metastatic malignant neoplasm involving the stomach. "In patients with primary gastric carcinomas, Laminin a4 subunit (LAMA4) expression is associated with high-grade tumors and predicts poor OS." (PMID 38542354, 2024). "LAMA4 gene expression is upregulated in gastric-cancer cells through the binding of the ZEB1 (Zinc finger E-box-binding homeobox 1) transcription factor to the LAMA4 promoter." (PMID 38542354, 2024). "In gastric cancer, LAMA4 is activated by the androgen receptor and enhances cell cisplatin resistance." (PMID 36539799, 2022). "For example, LAMA4, SFRP family members, ZHX2, and PAFAH1B3 were found to be associated with immune infiltration of gastric cancer." (PMID 35252219, 2021). "We investigated the effects of LAMA4 in gastric cancer (GC)." (PMID 34414238, 2021). "A number of proteins have been reported to play important roles in gastric cancer metastasis, such as ITGB1, ITGAV, and LAMA4." (PMID 36520032, 2023).
ovarian carcinoma (8 papers, 2018 to 2023). A malignant neoplasm originating from the surface ovarian epithelium. "It was reported that low methylation of LAMA4 was associated with a significantly poor progression-free survival in ovarian cancer." (PMID 34414238, 2021). "Overexpression of LAMA4, LAMB1, and LAMC1 mRNAs has been associated with lower overall survival (OS) and progression-free survival (PFS) in ovarian cancer." (PMID 38031074, 2023). "On the contrary, LAMA4 was markedly downregulated in ovarian cancer, and overexpression of LAMA4 significantly impaired ovarian cancer cell proliferation, invasion, and migration." (PMID 34414238, 2021). "A previous study using microarray has also shown a lower MEDAG and LAMA4 expression in ovarian cancer compared to normal epithelial cells." (PMID 29499737, 2018). "LAMA4 has also been observed to be downregulated in ovarian cancer cells." (PMID 37612452, 2023). "The predictors, LAMA4, CA11, MEDAG, NANOG, SPINT2, let-7b, miR23b, and miR29a were found to be sufficient to classify 87.5% and 100% of ovarian cancer (n = 8) and disease control (n = 10) groups, respectively." (PMID 29499737, 2018). "Three mRNAs, CA11, LAMA4, MEDAG, were .01–.28-fold lower expressed and two mRNA, SPINT2 and NANOG, were 3.2–5.8-fold higher expressed in ovarian cancer ascites versus peritoneal fluid EVs." (PMID 29499737, 2018). "In contrast to LAMA4, CA11, and MEDAG, the 2 mRNAs, SPINT2 and NANOG, were found to be increased in ovarian cancer ascites compared to peritoneal fluid EVs." (PMID 29499737, 2018). "Based on previous studies relating to these mRNA, CA11 and MEDAG may be involved in maintaining malignant ascites microenvironment, while LAMA4, NANOG and SPINT2 activities could regulate ovarian cancer progression and metastasis." (PMID 29499737, 2018).
pancreatic cancer (8 papers, 2019 to 2024). "To explore the clinical role of LAMA4 in pancreatic cancer, we examined the association between LAMA4 and clinicopathological factors in 140 pancreatic cancer patients." (PMID 32929348, 2020). "In particular, our in vitro and in vivo results showed that LAMA4 expression was highly correlated with cancer-associated fibroblasts (CAFs) level which may contribute to pancreatic cancer metastasis." (PMID 32929348, 2020). "Based on the association between LAMA4 and the extracellular microenvironment in our bioinformatic analysis, we proposed that CAFs infiltration in pancreatic cancer might be influenced by LAMA4-mediated extracellular microenvironment alteration." (PMID 32929348, 2020). "Not only does our work help provide insights into the mechanism(s) of LAMA4 upregulation and its association with advanced pancreatic cancer, it also holds the promise of yielding potential biomarker(s) and therapeutic targets for an improved management of pancreatic cancer." (PMID 32929348, 2020). "LAMA4 secreted from pancreatic cancer cells was shown to have a positive influence on the migration of fibroblasts in the tumor microenvironment." (PMID 34414238, 2021). "LAMA4 DNA methylation levels were negatively correlated with the tumor histologic grade in pancreatic cancer patients." (PMID 34414238, 2021). "Pancreatic cancer patients with higher levels of LAMA4 expression were more likely to have liver metastasis and worse survival." (PMID 34414238, 2021). "To confirm the reliability of microarray data, we next performed quantitative RT-PCR (qRT-PCR) and western blot to examine LAMA4 mRNA and protein levels in WT and HM pancreatic cancer cell lines." (PMID 32929348, 2020). "In our study, pancreatic cancer cells overexpressed LAMA4, which is a component of endothelial basement membranes, and its expression highly correlated with pancreatic tumor histologic grade and survival of patients." (PMID 32929348, 2020). "To further investigate LAMA4 gene expression pattern in pancreatic cancer, we next performed TCGA-GTEx conjoint database analysis to compare LAMA4 RNA expression between normal pancreatic tissues and pancreatic tumor tissues." (PMID 32929348, 2020). "To investigate the effect of LAMA4 in liver metastasis of pancreatic cancer cells, we first examined LAMA4 protein expression in pancreatic cancer cell lines." (PMID 32929348, 2020). "LAMA4 overexpression in aggressive pancreatic cancer and its metastatic potential as well as the relationship of LAMA4 to CAFs provide good prospects to our study." (PMID 32929348, 2020). "To further validate the relationship between LAMA4 and metastasis, we next examined the relationship between LAMA4 and metastasis in other cohorts of pancreatic cancer patients." (PMID 32929348, 2020). "As CAFs are a major component of the pancreatic cancer stroma and contribute to metastasis in pancreatic cancers 28, we next calculated the correlation between LAMA4 expression and infiltration level of CAFs." (PMID 32929348, 2020). "In the current study, we demonstrate for the first time that LAMA4 is involved in pancreatic cancer metastasis." (PMID 32929348, 2020). "The effects of LAMA4 knockdown in pancreatic cancer cells on CAFs viability and migration were evaluated." (PMID 32929348, 2020). "We next stably downregulated LAMA4 expression by shRNA in SUIT-2 and AsPC-1 human pancreatic cancer cells and confirmed downregulated LAMA4 at both mRNA and protein levels." (PMID 32929348, 2020). "We then examined the effects on LAMA4 knockdown on the liver metastasis ability of pancreatic cancer cells in vivo." (PMID 32929348, 2020). "In our study, both LAMA4 RNA and LAMA4 protein levels were highly correlated with pancreatic tumor histologic grade and patient survival in both clinical tumor tissues and bioinformatic analysis." (PMID 32929348, 2020).
pancreatic cancer (continued). "The pancreatic tumors on liver was smaller in the LAMA4-depleted SUIT2 and AsPC-1 group than in the WT control group on day 28 of IVIS examination." (PMID 32929348, 2020). "LAMA4 mRNA expression was significantly increased in pancreatic tumor tissues compared with normal pancreatic tissues (Wilcox test; p < 0.005)." (PMID 32929348, 2020). "To validate LAMA4 increase in pancreatic tumor tissues, we next examined LAMA4 protein expression in isolated human clinical specimens of pancreatic tumor tissue and normal tissue using IHC staining." (PMID 32929348, 2020). "We then examined LAMA4 expression in primary pancreatic tumor tissues and paired liver-metastatic tumor tissues by IHC staining." (PMID 32929348, 2020). "For the laminin subunits (LAMA3, LAMA4, LAMB3 and LAMC2) that were found to be associated with the prognosis of pancreatic cancer, we further analyzed their TCGA tumor tissue expression profiles." (PMID 31182680, 2019). "In the present study, we initially screened out four differentially expressed subunits (LAMA3, LAMA4, LAMB3 and LAMC2) of the laminin gene family that were found to be associated with the clinical outcome of pancreas cancer patients in TCGA." (PMID 31182680, 2019). "Hypomethylation of LAMA4 was identified as a marker of poor prognosis in pancreatic cancer." (PMID 35571032, 2022). "Elevated LAMA4 promoted pancreatic cancer cell liver metastasis." (PMID 36539799, 2022). "LAMA4 upregulation promotes hepatic metastasis in pancreatic cancers." (PMID 34503278, 2021). "We propose the possibility that pancreatic cancer cell-derived secreted LAMA4 could influence the recruitment or activation of CAFs, resulting in a favorable microenvironment that sustains pancreatic cancer metastasis or metastatic tumor growth in liver." (PMID 32929348, 2020). "Given the importance of TME in liver metastasis and the impact of LAMA4 on TME, we suggest that liver metastasis in pancreatic cancer may be influenced by LAMA4-mediated TME alterations." (PMID 32929348, 2020). "LAMA4 downregulation did not cause any effect on pancreatic cancer cell viability, migration or invasion in SUIT-2 cells and AsPC-1 cells." (PMID 32929348, 2020). "LAMA4 was overexpressed in tumor tissues compared to normal tissues in pancreatic cancer." (PMID 32929348, 2020). "Notably, LAMA4 DNA methylation levels were negatively correlated with tumor histologic grade in pancreatic cancer patients." (PMID 32929348, 2020). "We suggest that LAMA4-mediated CAFs recruitment and activation may contribute to pancreatic cancer metastasis." (PMID 32929348, 2020). "Furthermore, tumor-derived LAMA4 was highly positively correlated with recruitment of CAFs and had a positive effect on viability and migration of CAFs in pancreatic cancer." (PMID 32929348, 2020). "Interference with the recruitment or activation of CAFs might be achieved via LAMA4 manipulation, which might provide a potential therapeutic approach to pancreatic cancer." (PMID 32929348, 2020). "Downregulation of LAMA4 reduced the liver metastatic ability of pancreatic cancer cells in vivo." (PMID 32929348, 2020). "We next explored the biologic role of LAMA4 in pancreatic cancer." (PMID 32929348, 2020). "The CAFs and WT or LAMA4-depleted pancreatic cancer cell lines were co-cultured respectively." (PMID 32929348, 2020). "The correlation between LAMA4 and tumor severity might contribute to poor prognosis in patients with pancreatic cancer." (PMID 32929348, 2020). "Our findings indicate that LAMA4 may contribute to pancreatic cancer metastasis via recruitment or activation of CAFs." (PMID 32929348, 2020). "Furthermore, we examined the relation between LAMA4 DNA methylation status and pancreatic tumor histologic grade and survival by using TCGA dataset." (PMID 32929348, 2020). "Notably, downregulation of LAMA4 inhibited liver metastasis in a murine model of pancreatic cancer." (PMID 32929348, 2020).
pancreatic cancer (continued). "Thus, we suggest that LAMA4-mediated recruitment or activation of CAFs may contribute to the metastatic potential of pancreatic cancer." (PMID 32929348, 2020). "Our non-contact co-culture results indicated that LAMA4 knockdown in pancreatic cancer cells has a negative influence on the viability and migration of CAFs." (PMID 32929348, 2020). "However, the function and molecular mechanisms of LAMA4 in pancreatic cancer have not been systematically studied." (PMID 32929348, 2020).
cardiomyopathy (7 papers, 2019 to 2025). A disease of the heart muscle or myocardium proper. "Seven variants (41%) were detected in genes associated with cardiomyopathies including CSRP3, LAMA4, MYH6, MYBPC3, TNNI3, TNNI3K, and TNNT2." (PMID 39272661, 2024). "LAMA3-related diseases include laryngeal cartilage skin syndrome and epidermolysis bullosa, LAMA4-related diseases include cardiomyopathy, while LAMA5-related diseases include peripheral retinal degeneration and nephrotic syndrome." (PMID 32213190, 2020). "Mice lacking LAMA4 develop cardiomyopathy and have an increased frequency of sudden death upon stress; electron microscopy of these mice revealed malformed blood vessels and micro-circulation abnormalities." (PMID 30650640, 2019).
dilated cardiomyopathy (7 papers, 2021 to 2025). Cardiomyopathy which is characterized by dilation and contractile dysfunction of the left and right ventricles. "Heterozygous mutations in LAMA4 are causal to the syndromic disease dilated cardiomyopathy-1JJ." (PMID 38383672, 2024). "The LAMA4 gene is the causative gene of dilated cardiomyopathy 1JJ (OMIM #615235)." (PMID 35663266, 2022). "Pathogenic LAMA4 variants are associated with dilated cardiomyopathy." (PMID 34816733, 2021). "By combining volcano plot and GO analysis, we identified differentially expressed genes enriched in hypertrophic and dilated cardiomyopathy, including TTN, TPM3, CTTN, LAMA4, and ITGB1." (PMID 41214391, 2025).
glioma (7 papers, 2010 to 2024). A benign or malignant brain and spinal cord tumor that arises from glial cells (astrocytes, oligodendrocytes, ependymal cells). "We found that the glioma patients with higher expression of LAMA4 is significantly associated with shorter survival days (P-value <0.05)." (PMID 31118022, 2019). "LAMA‐4, Laminin Subunit Alpha 4, is specifically secreted by brain tumor cell lines and gliomas." (PMID 39440923, 2024). "Knockdown of LAMA4 suppressed glioma cell adhesion and migration and reduced cell invasiveness." (PMID 34414238, 2021). "Enhanced expression of laminin subunit alpha 4 and angiopoietin 2 in WHO grade II glioma was confirmed by staining of human tumor tissue microarrays." (PMID 35670981, 2022). "Further, antisense oligonucleotides against laminin-8 (LAMA4 and LAMB1) were found to block the invasion of glioma cells and neovascularization in vitro." (PMID 32571313, 2020). "Despite the documented roles of TGFB1, SPARC and LAMA4 in GBM progression and invasion, only the SPARC protein was identified in the two clinical glioma EV preparations profiled here." (PMID 27770278, 2017). "Other genes associated with mesenchymal phenotypes and glioma invasion, not yet formally linked to EMT, included laminin, alpha 4 (LAMA4) and fibroblast activation protein alpha (FAP)." (PMID 20646316, 2010).
hepatocellular carcinoma (6 papers, 2019 to 2025). A malignant tumor that arises from hepatocytes. "In vivo, LAMA4 with high expression was observed in human hepatocellular carcinoma tissues (n = 48) compared with the corresponding adjacent tissues, and the upregulation of LAMA4 was closely associated with tumor invasion and metastasis." (PMID 32489317, 2020). "In human hepatocellular carcinoma, LAMA4 with high expression was observed, and findings indicated that LAMA4 upregulation had a strong correlation with hepatocellular tumor invasion." (PMID 32489317, 2020). "Furthermore, overexpression of LAMA4 significantly impairs proliferation, invasion, and migration of ovarian, breast, and hepatocellular cancer cells." (PMID 36520032, 2023). "Another study found that high expression of LAMA4 may be a new marker of tumor invasion and metastasis in human hepatocellular carcinoma." (PMID 34456632, 2021). "For example, in hepatocellular carcinoma, LAMA4+ CD90+ endothelial CAFs induce senescence of CD8+ T cells, thereby suppressing anti-tumor immunity; conversely, targeting LAMA4 can reverse immunosuppression and enhance the efficacy of PD-1 blockade." (PMID 41445734, 2025). "We identified 4 hub genes, namely, LAMA4, POLA2, RAD51, and TYMS, which were used as the final variables, and found that AdaBoostClassifie was the best algorithm for the classification and diagnosis model of hepatocellular carcinoma." (PMID 37051625, 2023).
colorectal cancer (5 papers, 2018 to 2023). A primary or metastatic malignant neoplasm that affects the colon or rectum. "Elevation of LAMA4/LAMA5 protein ratio correlates with an increase in the permeability of the basal membrane as well as the metastatic and invasive potential of colorectal cancer." (PMID 31781574, 2019). "Surprisingly, there were several other pairs containing other than LAMA4, LAMC1, and LAMC2 genes with similar prognostic power in colorectal cancer." (PMID 29504916, 2018).
sarcoma (4 papers, 2019 to 2022). A usually aggressive malignant neoplasm of the soft tissue or bone. "To determine whether Tvax could induce T cell responses to naturally occurring cancer neoantigens, we expressed the Alg8 and Lama4 neoantigens identified in a methylcholanthrene-induced sarcoma fused to the LLO190 epitope and GFP in a retroviral construct." (PMID 34396986, 2021).
glioblastoma (3 papers, 2009 to 2018). The most malignant astrocytic tumor (WHO grade IV). "Clearly, cells expressing IRE1α RNase mutants heightened the expression of ECM markers characteristic of glioblastoma malignancy or invasion, including fibrillar collagens, the collagen cross-linker LOX and the proteins THBS1, YKL-40, DCN and LAMA4." (PMID 26325176, 2015).